ABCC6 (ATP binding cassette subfamily C member 6)
Diseases named in the same sentence as ABCC6 in open-access papers (continued):
Sharing a sentence is not in itself a finding about the gene and the disease.
Pseudoxanthoma elasticum (continued). "Although HI has not been associated with pseudoxanthoma elasticum, it has been reported in patients with generalized arterial calcification of infancy (OMIM 624473), which is also caused by recessive variants in ABCC6." (PMID 34148116, 2022). "However, since the lack of ABCC6 transport activity is the cause of ectopic mineralization in Pseudoxanthoma elasticum (PXE), the potential of harm deriving from reducing its activity should be carefully evaluated." (PMID 33918012, 2021). "A 24-year-old woman had pseudoxanthoma elasticum (PXE) with retinal pigmentary dystrophy due to maternal-originated ABCC6, and the patient has had no other identified systemic disorders to date." (PMID 33946315, 2021). "The involvement of ABCC6 in an autosomal recessive connective tissue disorder, pseudoxanthoma elasticum, is well established despite the fact that ABCC6 is not expressed in the tissue within which this disease occurs." (PMID 29385210, 2018).
calcification (16 papers, 2011 to 2024). Process by which organic tissue becomes hardened by the physiologic deposit of calcium salts. "Medical researchers have found that infants who have mutations in the ABCC6 gene can develop a serious condition of systemic arterial calcification." (PMID 38248755, 2023). "We selected cases studies particularly to validate that MouseFM can identify experimentally validated variants and genes, such as the Tyr variant rs31191169 for albinism and the gene Abcc6 for dystrophic cardiac calcification." (PMID 33763305, 2021). "Due to natural genetic loss of Abcc6, the causal gene for cardiac calcification, C3H mice have reduced plasma levels of inorganic pyrophosphate (PPi), a potential calcification inhibitor." (PMID 29643466, 2018). "Abcc6 deficiency was recently linked to an acute cardiac calcification phenotype referred to as dystrophic cardiac calcification (DCC) in several inbred strains of mice including C3H/HeJ and DBA/2J." (PMID 28891970, 2017). "There is a similar prevalence of GACI phenotypes between ENPP1 and ABCC6 mutations, including arterial calcification (77.2% and 89.5%, respectively), organ calcification (65.8% and 84.2%, respectively), and cardiovascular complications (58.4% and 78.9%, respectively)." (PMID 38165475, 2024). "ABCC6 deficiency mainly causes PXE (MIM#264800), whereas defective ENPP1 (the key enzyme for PPi production) leads to generalized arterial calcification of infancy (GACI, MIM#208000)." (PMID 38392293, 2024). "Considering the inheritable calcification syndromes resulting from dysfunctional ABCC6, this transporter is now viewed as a key player in ectopic mineralization pathologies, but it is unclear how ABCC6 contributes to this process." (PMID 28383515, 2017). "Dietary supplementation with Mg in Abcc6−/− mice was shown to contribute to reduce calcifications but the Mg concentrations used were more elevated than acceptable for human use." (PMID 28891970, 2017). "In contrast, calcifications resulting from Abcc6 inactivation were augmented by crossing Abcc6−/− mice with Nt5e−/− mice and Abcc6−/− mice have reduced Nt5e expression in their arteries." (PMID 28891970, 2017). "Abcc6 was a promising candidate gene because of its genomic location (chr 7: 45.9Mbp) and its known role in dystrophic cardiac calcification." (PMID 26375467, 2015). "Moreover, skeletal and cardiac muscles of D2-mdx mice exhibit calcifications, due to the presence of the Dyscalc loci in the ATP Binding Cassette Subfamily C Member 6—ABCC6 and Epithelial Membrane Protein 3—EMP3 genes." (PMID 39535998, 2024). "The fact that ABCC6 is involved in a pathway of extracellular nucleotide metabolism appears of paramount importance because it establishes a link between PXE and generalized arterial calcification of infancy (GACI) or calcification of joints and arteries (ACDC)." (PMID 28891970, 2017).
Generalized arterial calcification of infancy (10 papers, 2012 to 2025). "ABCC6 mutations have also been connected to generalized arterial calcification of infancy (GACI; OMIM 173335), which is linked to ENPP1 mutations that regulate bone mineralization." (PMID 40725385, 2025). "Generalized arterial calcification of infancy (GACI) is a rare disorder caused by ENPP1 or ABCC6 variants." (PMID 34355424, 2021). "Also supportive of ABCC6’s role in preventing calcification is that in some cases ABCC6 mutations result in a more severe set of clinical symptoms known as generalized arterial calcification of infancy 2 (GACI2, OMIM 614473)." (PMID 33768091, 2021). "Deleterious mutations in human ABCC6, ENPP1, NT5E genes cause PXE, generalized arterial calcification of infancy (GACI), and arterial calcification respectively." (PMID 26375467, 2015).
atherosclerosis (8 papers, 2019 to 2025). A disease characterized by the build-up of fatty material and calcium deposition in the arterial wall resulting in partial or complete occlusion of the arterial lumen. "Detailed mechanistic studies are warranted to clarify how ABCC6 deficiency leads to dyslipidemia and atherosclerosis." (PMID 40725385, 2025). "Mechanistically, ABCC6 deficiency is implicated in dyslipidemia and atherosclerosis, further exacerbating cerebrovascular risks." (PMID 40725385, 2025). "In fact, the study reveals that ABCC6 deficiency contributes significantly to dyslipidemia and atherosclerosis in both mice and humans." (PMID 40725385, 2025). "Overall, the findings establish that ABCC6 plays a crucial role in modulating plasma lipoproteins and the hapolinsufficient development of atherosclerosis, with implications for understanding the cardiovascular risks associated with ABCC6 mutations." (PMID 40725385, 2025). "To explore this possibility, we conducted a study presenting compelling evidence obtained with both mouse models and PXE patients that indeed ABCC6 deficiency promotes dyslipidemia and atherosclerosis in a haploinsufficient manner, with significant penetrance." (PMID 38392293, 2024). "There is evidence that pathogenic ABCC6 variants cause not only arteriosclerosis but also atherosclerosis by affecting lipoprotein metabolism." (PMID 35525997, 2022). "Furthermore, we examined plasma lipoproteins, vascular calcification, carotid intima-media thickness and atherosclerosis in a cohort of PXE patients with ABCC6 mutations and compared results to dysmetabolic subjects with increased cardiovascular risk." (PMID 33594095, 2021). "ABCC6 deficiency promotes ectopic calcification; however, circumstantial evidence suggested that ABCC6 may also influence atherosclerosis." (PMID 33594095, 2021). "Elevated levels of some of these biomarkers have been linked to increased vascular inflammation and remodeling, which are critical factors in conditions like atherosclerosis and hypertension and could be enhanced by the decrease or loss of function of the ABCC6 gene product." (PMID 40725385, 2025). "We found that ABCC6 deficiency causes changes in lipoproteins, with decreased HDL cholesterol in both mice and humans, and induces atherosclerosis." (PMID 33594095, 2021). "Our study showed a novel physiological role for ABCC6, influencing plasma lipoproteins and atherosclerosis in a haploinsufficient manner, with significant penetrance." (PMID 33594095, 2021). "Despite the noted dyslipidemia and atherosclerosis, the study found that ABCC6 deficiency did not significantly affect vascular calcification associated with atherosclerosis." (PMID 40725385, 2025). "One of the additional pathways contributing to vascular calcification in PXE could therefore be atherosclerosis due to ABCC6-related dyslipidemia." (PMID 38221909, 2024). "Understanding the full molecular ramification of ABCC6 deficiency represents an opportunity to better treat PXE/GACI and also ectopic calcification when it manifests as a co-morbidity in much more common pathologies such as diabetes, kidney failure, atherosclerosis or simply aging." (PMID 38392293, 2024). "•PPi levels do not explain arterial calcification, so atherosclerosis due to ABCC6-related dyslipidemia could contribute." (PMID 38221909, 2024). "However, we found that the absence of ABCC6 does not influence overall vascular mineralization induced with atherosclerosis." (PMID 33594095, 2021). "Absence of endothelial dysfunction in hypertensive Abcc6−/− mice may nevertheless suggest that PXE-associated PAD contrasts with other calcific metabolic diseases such as diabetes, chronic renal insufficiency and atherosclerosis, which incur early onset of endothelial dysfunction." (PMID 31704980, 2019).
dyslipidemia (7 papers, 2015 to 2025). "In light of a recent publication showing pro-atherogenesis and dyslipidemia effects associated with ABCC6 deficiency in both ABCC6−/− mice and PXE patients, our data bring into question the cost/benefit ratio for the use of these drugs in PXE." (PMID 35566717, 2022). "PXE patients with moderately severe type IV hyperlipoproteinemia were screened and it was shown that ABCC6 p.(R1164X) nonsense mutation and the ABCC6 p.(R1268Q) SNP are associated with dyslipidemia, characterized by high plasma triglyceride and low HDL cholesterol." (PMID 26356190, 2015). "Multiple lines of evidence in the literature indicated a pathologic correlation between ABCC6 function and dyslipidemia." (PMID 38392293, 2024). "It has been hypothesized that the ABCC6 gene could be related to dyslipidemia, which could contribute to vascular calcification seen in PXE." (PMID 38221909, 2024).
Hypertension (7 papers, 2015 to 2025). The presence of chronic increased pressure in the systemic arterial system. "The cardiovascular complications of GACI (ABCC6 mutation) are mostly reported as heart failure, hypertension, and respiratory failure, while severe hypertension like our case has only been reported in rare cases." (PMID 38165475, 2024). "While CV calcifications is a hallmark of PXE, Abcc6 deficiency allowed extensive fibrosis to occur in mice subjected to DOCA-Salt hypertension." (PMID 31704980, 2019). "Intermediate prevalence (37.4%) of hypertension among cat5 deletions implicates ABCC6, suggesting that multiple genes contribute to hypertension risk at 16p13.11." (PMID 38185688, 2024). "Abcc6 loss-of-function is associated with greater cardiovascular calcification and fibrosis in mice subjected to DOCA-Salt hypertension." (PMID 31704980, 2019). "Alterations in BMP signaling are likely to contribute to the effects of ABCC6 deficiency in cardiovascular system since BMPs have been associated with hypertension, non-laminar flow, endothelial inflammation, angiogenesis, and calcification in the vascular wall as well as the myocardium." (PMID 25893161, 2015). "Beyond infancy, ABCC6 genetic testing should be considered not only in those with characteristic cutaneous or ocular PXE lesions, but also in children presenting with stroke, seizure, or hypertension of undetermined etiology." (PMID 41257790, 2025).
Stroke (7 papers, 2012 to 2025). Sudden impairment of blood flow to a part of the brain due to occlusion or rupture of an artery to the brain. "Nevertheless, a significantly higher presence of pathogenic ABCC6 variants in the stroke patient cohort compared to healthy age- and sex-matched controls was demonstrated, independently of other risk factors." (PMID 40725385, 2025). "In fact, the stroke phenotypes linked to pathogenic ABCC6 variants are varied, primarily including large vessel disease, followed by cardioembolic stroke and SVD, aligning with previous findings in PXE patients." (PMID 40725385, 2025). "Additionally, several heterozygous ABCC6 variants are an established risk factor for ischemic stroke and are included on pediatric stroke gene panels." (PMID 41257790, 2025). "At least one cohort study raised noted pathogenic mutations of ABCC6 and the risk of stroke." (PMID 40725385, 2025). "Another potential mechanism linking ABCC6 with stroke comes from animal studies suggesting there is an indirect pathway involving the classic vascular risk factors." (PMID 40725385, 2025). "Interestingly, in the case–control study, only one out of sixteen patients had an SVD-related stroke pattern, and Del23-29 (Exon 23-29) was found in ABCC6 gene." (PMID 40725385, 2025).
coronary artery disease (6 papers, 2020 to 2025). "Overall, the prevalence of CAD in this cohort was similar to that of the European population (7.3%) aged 40 to 70, thus coronary artery diseases cannot be specifically associated with ABCC6 deficiency." (PMID 38392293, 2024). "Mutations in the ABCC6 gene can lead to an increased prevalence of coronary artery disease." (PMID 40943414, 2025). "ABCC6 sequence variations are correlated with altered HDL cholesterol levels and an elevated risk of coronary artery diseases." (PMID 33483533, 2021). "Furthermore, c.3421C>T in ABCC6 plays a role in vascular calcification in chronic kidney disease (CKD), and its association in heterozygous state with ischemic heart disease has been demonstrated in some case–control studies (though it was not confirmed in further meta-analysis study)." (PMID 40565367, 2025).
hepatoma (5 papers, 2008 to 2023). "The role of ABCC6 in cancer has often been controversial; therefore, to further understand its role in hepatoma biology, we investigated the effect of ABCC6 gene silencing on the HepG2 cells transcriptome." (PMID 38003580, 2023). "-233 bp), known to confer high-level ABCC6 expression in HepG2 hepatoma cells, is completely conserved in the putative ABCC6P1 promoter region." (PMID 18405356, 2008). "Regarding the role of ABCC6 in hepatocellular carcinoma, a recent study demonstrated that low expressions of ABCC6 and other ABCC transporters are correlated with poor prognoses in liver hepatocellular carcinoma, identifying these proteins as potential diagnostic markers." (PMID 38003580, 2023). "Moreover, as in hepatoma cells, we found a correlation between ABCC6 and NT5E expression, the ectonucleotidase responsible for the production of adenosine, and we assessed basal level of expression of both genes." (PMID 35645325, 2022). "The concomitant administration of ABCC6 inhibitors and tyrosine kinase inhibitors has been suggested as a therapeutic option for the treatment of chronic myeloid leukemia, and it could certainly be interesting to evaluate its potential on hepatoma cell cultures." (PMID 38003580, 2023). "We first validate the ABCC6 antibody specificity by conducting immunofluorescent analyses in human hepatocellular carcinomas cells (HepG2) and mouse renal tubular epithelial cells (IMCD3), in which ABCC6 protein was previously detectable." (PMID 33383974, 2020). "There is no doubt that the enormous amount of data available from transcriptomic analysis opens up the possibility of investigating any other not yet explored role of ABCC6, which might assume the role of a regulator in the biology of hepatocellular carcinoma." (PMID 38003580, 2023).
hemoglobinopathies (4 papers, 2012 to 2021). "The patients in the present study with heterozygous monoallelic ABCC6 mutations did not have symptoms of hemoglobinopathies, and Hb levels were within normal limits." (PMID 34440381, 2021).
liver cancer (4 papers, 2022 to 2023). An epithelial or non-epithelial malignant neoplasm that arises from the liver. "RT-qPCR and Western blotting were performed to evaluate the effect of ABCC6 silencing on some liver cancer-related genes." (PMID 38003580, 2023). "Our study provides profound insights into the behavior of ABC transporter family genes in various HCC cohorts, identifies ABCC6 as a potential biomarker for early-stage HCC diagnosis, and highlights the significance of ABCC6 in liver cancer progression." (PMID 35280774, 2022).
rickets (4 papers, 2021 to 2024). Bone softening and weakening usually caused by deficiency or impaired metabolism of vitamin D. Deficiency of calcium, magnesium, or phosphorus may also cause rickets. "There has only been one case of a hypophosphatemic rickets in a patient with GACI who had a monoallelic ABCC6 mutation." (PMID 38248755, 2023). "It is not clear why there is an overlapping GACI phenotype (arterial calcification with cardiovascular complications) between ENPP1 and ABCC6 deficiencies but a difference in the eventual development of rickets with ENPP1 variants." (PMID 34355424, 2021). "Despite the similar calcification phenotype between ENPP1 and ABCC6 deficiencies, there was a disparity in the mortality rate and the presence of rickets in the ENPP1 versus ABCC6 cohorts." (PMID 34355424, 2021). "But in contrast to the ABCC6 mutations, the incidence of ENPP1 mutations was higher in terms of mortality, rickets, joint calcification, hearing complications, and neurological complications." (PMID 38165475, 2024). "Clinical signs of rickets were reported in 40 of 127 affected individuals (36.7%) in the full data set; this prevalence was higher in affected individuals with ENPP1 variants (36/38 [48.6%]) than in those with ABCC6 variants (3/18 [16.7%])." (PMID 34355424, 2021). "Further analysis of the rickets observed in the three ABCC6‐deficient affected individuals disclosed that it was not accompanied by hypophosphatemia and hyperphosphaturia and was likely a consequence of etidronate administration." (PMID 34355424, 2021). "It is worth noting that rickets has not been reported in ABCC6‐deficient adults diagnosed with PXE." (PMID 34355424, 2021).
beta thalassemia (3 papers, 2013 to 2019). Beta-thalassemia (BT) is characterized by deficiency (Beta+) or absence (Beta0) of synthesis of the beta globin chains of hemoglobin (Hb). "To date, the causes of these alterations in beta-thalassemia patients are not known, but it has been suggested that they could be the consequence of oxidative stress-driven epigenetic regulatory mechanisms producing an ABCC6 down-regulation." (PMID 32039214, 2019).
bladder cancer (3 papers, 2015 to 2020). "Similarly, hypermethylation of the ABCC6 gene was identified in urine of bladder cancer patients." (PMID 26459268, 2015). "Accordingly, methylation profiling of urine sediments, to detect the top four frequently methylated genes, namely SALL3, CFTR, ABCC6, and HPP1, together can detect bladder cancer with 82.6% sensitivity and 100% specificity." (PMID 30901947, 2019).